INS (insulin)
Diseases named in the same sentence as INS in open-access papers (continued):
Sharing a sentence is not in itself a finding about the gene and the disease.
Insulin resistance (continued). "In particular, hsa-miR-3148 was reported to impair the insulin signaling pathway by downregulating IRS1, causing insulin resistance." (PMID 37762604, 2023). "The activation of JNK is primarily responsible for the changes in insulin signaling pathways that contribute to insulin resistance." (PMID 38140341, 2023). "Insulin resistance, in turn promoted the development of cognitive dysfunction because of insulin signaling impairment." (PMID 37488554, 2023). "In this review, insulin resistance is defined as a curve of responding to insulin dose with increased EC50 (half maximal effective concentration), with or without declined maximal response." (PMID 37664840, 2023). "Insulin resistance is often accompanied by an increase in endogenous insulin synthesis as a compensatory mechanism." (PMID 37346347, 2023). "Obesity is one of the leading T2D risk factors, as increased adipose tissue mass can lead to impaired insulin secretion or insulin resistance." (PMID 37040172, 2023). "The primary causal factor for the progression of T2D has been believed to be insulin resistance induced by the interaction of insulin resistance genes and obesity which drives the hypersecretion of beta cells for insulin compensation." (PMID 36848379, 2023). "The PI3K inhibition prevented ACSL gene hyper‐expression, fat accumulation, oxidative stress and insulin resistance through the reduction of insulin signalling in mouse hepatocytes." (PMID 36639836, 2023). "A decrease in miR-423-5p expression, a drop in whole-body insulin resistance, and an increase in liver insulin sensitivity have been demonstrated." (PMID 37511248, 2023). "Moreover, it has been found that stress hyperglycemia mediated by stress-induced insulin resistance following severe trauma is associated with both infection and death in critically injured patients, whereas enteral feeding modulates metabolic responses, attenuating the insulin resistance." (PMID 37125037, 2023). "Insulin resistance leads to a rise in hepatic glucose secretion and a reduced muscle glucose uptake, which consequently triggers pancreatic β-cells to boost insulin production." (PMID 37762544, 2023). "The main reason for this is that palmitic acid is thought to induce insulin resistance by inhibiting insulin signaling and activating protein kinases." (PMID 38069273, 2023). "Insulin resistance is defined as the reduced ability of insulin to promote glucose uptake and storage by target organs such as the liver, skeletal muscle, or AT." (PMID 37445956, 2023). "A high-fat diet is associated with metabolic endotoxemia caused by serum LPS, resulting in obesity and insulin resistance, and high serum LPS enhances TNF-α and inhibits insulin signals." (PMID 36900540, 2023). "Insulin resistance (IR) refers to the decrease in insulin sensitivity that requires an increase in the amount of insulin to achieve its normal function." (PMID 37179333, 2023). "When insulin resistance occurs, the insulin-responding tissues and organs cannot sensitively utilize glucose." (PMID 36904097, 2023). "Leptin is positively correlated with obesity and insulin resistance, while adiponectin shows a good ability to enhance insulin sensitivity and counteract the development of diabetes." (PMID 36790383, 2023). "Adipose tissue insulin resistance is characterised by impaired suppression of lipolysis and stimulation of lipogenesis in the presence of high circulating insulin." (PMID 37491534, 2023). "Concomitantly, HFD-induced glucose intolerance and insulin resistance were significantly accelerated in pregnant mHFD mice, indicating impaired glucose tolerance and insulin sensitivity." (PMID 37973927, 2023). "Under insulin resistance conditions, berberine exhibited a synergistic effect on insulin-induced glucose uptake and GLUT4 translocation." (PMID 36770960, 2023).
Insulin resistance (continued). "Defects in insulin-stimulated GLUT4 translocation during insulin resistance can be due to impaired sorting of GLUT4 into the GSVs and the downregulation of regulatory proteins of GSV trafficking, such as VAMP2 and sortilin." (PMID 37229459, 2023). "Firstly, insulin supplementation was incorporated into the study in order to implement a model for insulin resistance and related hyperinsulinemia, both often observed in obese, prediabetic or PCOS patients that are prone to EC development." (PMID 37313172, 2023). "Increased insulin resistance, weakened Glut-4 translocation, and decreased intracellular glucose uptake following insulin stimulation in obesity are a major defect (Szymczak-Pajor and Śliwińska, 2019)." (PMID 37529167, 2023). "When compared with placebo, women receiving probiotic supplements had significantly lower mean fasting serum glucose, fasting serum insulin, homeostatic model assessment for insulin resistance (HOMA-IR), triglycerides, total cholesterol, and VLDL levels." (PMID 37049473, 2023). "Physiological insulin resistance occurs during adolescence when insulin sensitivity decreases by 25–50%." (PMID 37892696, 2023). "It has been shown that the reduction of SIRT1 expression is related to the development of insulin resistance, and increased its expression improves insulin sensitivity in skeletal muscle." (PMID 38027557, 2023). "It has been shown that ferroptosis in pancreas β cells leads to decreased insulin secretion; and ferroptosis in the liver, fat, and muscle induces insulin resistance." (PMID 36882414, 2023). "For direction FG ← T2D, it is possible that the pancreas makes more insulin to make up for insulin resistance in T2D, and blood sugar levels build up overtime." (PMID 37200398, 2023). "On the other hand, hypothyroidism interferes with the action and metabolism of insulin, and induces insulin resistance." (PMID 36830883, 2023). "The resultant overactivation of the renin-angiotensin-aldosterone system (RAAS) leads to systemic and vascular insulin resistance through insulin-mediated Glut-4 translocation and impairment of endothelial nitric oxide production." (PMID 37102024, 2023). "Over time, this increase in androgens leads to decreased insulin sensitivity, which creates an environment where the body must secrete more insulin in order to compensate, leading to the development of insulin resistance." (PMID 37569074, 2023). "Insulin resistance leads to increased insulin secretion to compensate; this state is known as hyperinsulinemia." (PMID 37664840, 2023). "In this review, we delve into the significant roles of NOXs in insulin secretion, insulin resistance, and ferroptosis." (PMID 38203517, 2023). "In contrast, type 2 diabetes (T2D) is featured by insulin resistance and decreased insulin production." (PMID 37780623, 2023). "At the cellular level, the pathophysiology of T2DM involves impaired insulin secretion and insulin resistance." (PMID 37745252, 2023). "Resistin is a pro-inflammatory adipokine mediating hepatic insulin resistance, and named for its role in antagonizing insulin." (PMID 37266440, 2023). "Asynchrony of the central and the peripheral circadian clocks was associated with reducing insulin and glucagon-like peptide 1 (GLP-1) secretion, insulin resistance, β-cell proliferation, and β-cell apoptosis." (PMID 36909337, 2023). "During the natural course of T2DM, the expansion of adipose tissue results in a defect in insulin sensitivity (i.e., insulin resistance), with decreased glucose uptake and increased hepatic glucose production, leading to fasting hyperglycemia." (PMID 37627476, 2023). "After six weeks of dietary intervention, mice were subjected to an Insulin Tolerance Test (ITT) to assess the effects of fraction supplementation on HFHS diet-induced insulin resistance." (PMID 37629151, 2023). "Unfortunately, due to insulin resistance in these patients, high doses of insulin are needed to lower blood sugar." (PMID 37828117, 2023).
Insulin resistance (continued). "Deficiency in Xbp1 in mice results in insulin resistance, further supporting that the Xbp1/ER stress/HBP axis plays a pivotal role in maintaining insulin sensitivity." (PMID 37107691, 2023). "The relative excess of insulin leads to insulin resistance (IR) due to decreased receptor availability." (PMID 37446104, 2023). "T2D is characterized by diminished insulin secretion from pancreatic islets and insulin resistance in peripheral organs." (PMID 37111216, 2023). "As mentioned, hyperglycemia and insulin resistance lead to elevated ROS production in β-cells as a result of an increased rate of oxidative phosphorylation and insulin synthesis, respectively." (PMID 37237860, 2023). "In states of insulin resistance, magnesium levels decrease prior to the onset of reduced insulin reactivity in platelets." (PMID 37960200, 2023). "Resistin also has a hand in the development of insulin resistance due to its’ role in interfering with insulin action." (PMID 36830032, 2023). "Waist circumference, BMI, FPG, blood lipids, C-peptides, insulin, inflammatory factors, insulin resistance index (HOMA-IR)[HOMA-IR = FPG (mmol/L) × FINS (mIU/L)/22.5], and the subcutaneous and visceral fat contents of the upper abdomen will be measured by MRI." (PMID 37076915, 2023). "Insulin resistance is defined by the diminished response to insulin that occurs as a response to certain genetic and/or environmental factors." (PMID 36901787, 2023). "Carotenoids can regulate insulin resistance and promote insulin secretion to decrease abdominal fat accumulation through the regulation of hormone-sensitive lipase." (PMID 38037060, 2023). "The mechanistic studies in rodents show that hepatic lipid accumulation suppresses insulin signaling and, conversely, insulin resistance stimulates hepatic lipid accumulation." (PMID 37242206, 2023). "In our study logistic regression model analysis showed that fasting insulin and insulin resistance were statistical significant predictors of OP among the NAFLD group." (PMID 36928441, 2023). "Recent large prospective and cross-sectional cohort studies have also revealed close associations between elevated blood levels of BCAAs and insulin resistance, homeostasis model assessment (HOMA) insulin sensitivity and HbA1c level." (PMID 37755297, 2023). "In their study, bilirubin levels showed a significant inverse relationship with HbA1c (r = -0.70; p< 0.05), insulin levels, insulin resistance, total cholesterol, low-density lipoprotein (LDL), and triglycerides." (PMID 38406782, 2023). "We observed that insulin-regulated dephosphorylation was widely dysregulated in all 3T3-L1 insulin resistance models." (PMID 36808134, 2023). "We also calculated the HOMA-IR (Homeostatic Model Assessment for Insulin Resistance) by measuring fasting insulin- and glucose." (PMID 37060010, 2023). "In the blood, with increased insulin levels and insulin resistance in the liver and tissues, free fatty acids (FFAs) contribute to fat buildup, oxidative stress, inflammation, and hyperglycemia." (PMID 37241737, 2023). "In another form, the inability of β cells to synthesize or increase insulin levels sufficiently to stimulate glucose uptake in the face of insulin resistance leads to type 2 diabetes (T2D)." (PMID 38027148, 2023). "On one hand, CFRD, a complex and multifactorial disease, attributing to insulin secretion insufficiency and peripheral insulin resistance, represents capacity of dealing with carbohydrate." (PMID 38186649, 2023). "Insulin resistance is characterized by normal circulating insulin with decreased responsiveness to target tissues, which can cause persistent production of insulin and subsequent secondary hyperinsulinemia." (PMID 36734198, 2023). "It is well known that chronically elevated plasma insulin seen in obesity and type 2 diabetes can result in peripheral insulin resistance." (PMID 36979453, 2023).
Insulin resistance (continued). "Prevalence of insulin resistance decreased from 81.8% to 50.0% (p = 0.023), and low insulin sensibility reduced from 77.3% to 50.0% (p = 0.04)." (PMID 38063544, 2023). "Insulin resistance (HOMA-IR) was calculated using the formula- fasting glucose (mg/dL) x fasting insulin (μIU/mL)]/405." (PMID 37362491, 2023). "Insulin resistance and reduced insulin secretory capacity are core pathophysiological features of T2DM." (PMID 37514025, 2023). "In contrast, we did not observe relationships between plasma ZAG with either measures of glucose tolerance (e.g., fasting glucose and insulin or areas under the curve) or insulin resistance by HOMA-IR." (PMID 37830580, 2023). "Insulin resistance is a fundamental pathological feature of type 2 diabetes, often exacerbated by the impairment of insulin signaling." (PMID 37372538, 2023). "Recent strong evidence points to a role for VDD in the etiology of insulin resistance and insulin secretion abnormalities, with potential interference with T2DM as a result." (PMID 38073984, 2023). "Insulin resistance plays a key role in the onset and progression of PCOS and DG is reportedly associated with insulin-related signaling pathways and is a predictor of insulin resistance." (PMID 37124226, 2023). "In rodent models developed for exploring PAI-1’s physiological roles, specific PAI-1 overexpression in adipocytes causes insulin resistance, whereas specific PAI-1 deletion in adipocytes improves insulin action." (PMID 38136564, 2023). "The study showed that an excess of epinephrine can affect glucose metabolism mainly through impaired insulin secretion, instead of an excess of norepinephrine which can have a prevalent effect in terms of increased insulin resistance." (PMID 36982228, 2023). "In pregnant women, urinary isoflavones were found to be negatively correlated with fasting glucose, insulin, and the Homeostatic Model Assessment of Insulin Resistance (HOMA-IR)." (PMID 38115881, 2023). "Regarding Cer, their role in the pathogenesis of insulin resistance is better established, and it is known that they are able to antagonize the insulin-dependent glucose uptake." (PMID 37143040, 2023). "Characterized by insulin resistance and insufficient insulin secretion, T2DM has become a serious global health burden." (PMID 36986139, 2023). "In both the larval and adult stages of Drosophila, characteristics similar to insulin resistance, such as metabolic disorders and disrupted insulin signaling, can be replicated." (PMID 38002116, 2023). "Unexpectedly, however, we observed that cardiac CTRP9 overexpression induced a state of systemic insulin resistance with increased serum insulin levels." (PMID 36766785, 2023). "Insulin resistance impairs the function of insulin-dependent hormone-sensitive lipase and lipoprotein lipase, which are involved in lipid metabolism, whereas insulin cannot act effectively due to obesity and dyslipidaemia." (PMID 37152969, 2023). "Like rodents, bears, and hedgehogs, dwarf lemurs can show signatures of lean-season insulin resistance, including elevated fasting insulin and HOMA-IR values, lower fasting glucose, and reduced glucose tolerance compared the fattening and/or active seasons." (PMID 37745231, 2023). "For example, visceral WAT is related to the pathophysiology of obesity, dyslipidemia, and insulin resistance, while subcutaneous adipose tissue is related to insulin sensitivity." (PMID 37755259, 2023). "Low levels of insulin or IGF-1 and insulin resistance cause the inhibition of Akt phosphorylation and subsequent reductions in phosphorylated GSK3β, resulting in the degradation of β-catenin proteins." (PMID 37569816, 2023). "Insulin resistance is a pathological condition, often a consequence of excess body weight, in which cells fail to respond to insulin, resulting in high glucose in the tissues." (PMID 37924091, 2023).
Insulin resistance (continued). "In a rodent model of obesity and insulin resistance, Neb improved myocardial remodeling, diastolic dysfunction and insulin metabolic signaling by inhibiting myocardial NADPH oxidase-mediated superoxide formation." (PMID 37998760, 2023). "There is evidence elevations in glucocorticoids contribute to insulin-resistance via increases in pancreatic islet proliferation and volume, insulin secretion capacity, and islet chaperone expression." (PMID 37153459, 2023). "High insulin response accompanies higher fat deposition, elevated lipid profile, and insulin resistance." (PMID 36915133, 2023). "Under conditions of insulin resistance, the body compensates by augmenting insulin secretion to counteract this response, resulting in elevated blood insulin levels." (PMID 37782659, 2023). "Herman and colleagues reported that adipose ChREBPβ is highly regulated in insulin resistant states implying a manner to predict insulin resistance." (PMID 36923222, 2023). "These inflammatory factors further activate the macrophages and impair insulin signaling in adipocytes, leading to systemic insulin resistance." (PMID 37522129, 2023). "Insulin resistance refers to the decreased sensitivity of insulin target tissue (adipose tissue, skeletal muscle, liver) to insulin, which is an important pathological change in prediabetes." (PMID 38129878, 2023). "Insulin resistance (IR) and the metabolic syndrome are complex metabolic traits defined as decreased response to insulin in tissues." (PMID 37773140, 2023). "Proinflammatory cytokines lead to insulin resistance by reducing insulin sensitivity, inhibiting insulin signaling, and enhancing the inflammatory response of the host immune system to dental plaque according to this model." (PMID 37231396, 2023). "CRP is stimulated by IL-1β, TNF-α and IL-6 in the liver, which act together to activate serine and threonine kinases to suppress insulin signal transduction and thus promote insulin resistance." (PMID 37891561, 2023). "While one meta-analysis demonstrated within-group benefits for exercise on hepatic insulin sensitivity, the efficacy for improving glycaemic control and the Homeostatic Model Assessment for Insulin Resistance (HOMA-IR) in people with MAFLD is inconsistent." (PMID 37695493, 2023). "Insulin resistance (IR) is a pathological physiological state characterized by diminished sensitivity in the peripheral tissues to insulin, which is often prevalent in patients with sepsis and manifests as elevated insulin levels and reduced sensitivity." (PMID 37940931, 2023). "As such, our data reaffirmed that DCI preferentially recovers insulin sensitivity in case of insulin resistance." (PMID 36615188, 2023). "In vitro, RBM15 suppressed insulin sensitivity and increased insulin resistance through m6A-regulated epigenetic inhabitation of CLDN4." (PMID 36803098, 2023). "This review article summarizes the changes in miRNAs involved in beta cell function, insulin secretion, glucose tolerance, and insulin function in obesity, inflammation, and insulin resistance states." (PMID 37329278, 2023). "There is no indication of increased HK2 expression at the mRNA and protein level in the skeletal muscle and adipose tissues in clinical insulin resistance and some reports of decreases, likely due to decreased insulin-dependent expression." (PMID 38292764, 2023). "The down-regulation of mTOR by PA can contribute to inhibiting Akt phosphorylation and the dysregulation of insulin signaling, adding another layer of complexity to the development of insulin resistance." (PMID 38203517, 2023). "Increased maternal insulin resistance calls for pancreatic beta cells to adapt and compensate by secreting more insulin." (PMID 37049394, 2023). "A HOMA-IR result between 1.0 and 1.9 signifies early insulin resistance, indicating that the body's cells are starting to show some resistance to the effects of insulin." (PMID 38024834, 2023).